BECN1 (beclin 1)
Diseases named in the same sentence as BECN1 in open-access papers (continued):
Sharing a sentence is not in itself a finding about the gene and the disease.
ovarian carcinoma (146 papers, 2011 to 2026). A malignant neoplasm originating from the surface ovarian epithelium. "Beclin-1 is monoallelically deleted in 40%–70% of human breast, prostate, and ovarian cancers, though biallelic mutations in Beclin-1 are rare in human tumors." (PMID 39403142, 2024). "Initial evidence for a possible direct connection between autophagy and cancer came from the discovery of Beclin-1 as a haploinsufficient tumor suppressor with mutations in cancers of the ovary, small intestines, and skin." (PMID 36899946, 2023). "For example, heterozygous deletions of BECN1 (Atg6), a member of the ATG gene family involved in autophagosome initiation, have been reported in human prostate, breast, and ovarian cancers, and Becn1 deficiency led to spontaneous tumor development in mice." (PMID 35725745, 2022). "Consistently, BRCA1 deficient ovarian cancer cells were highly dependent on BECLIN 1-dependent autophagy for survival, and rapidly underwent cell death upon autophagy disruption." (PMID 33670664, 2021). "Several studies on human prostate, breast, and ovarian cancers, displayed partial monoallelic loss in one essential autophagy gene, ATG6/Beclin-1." (PMID 34445354, 2021). "Autophagy was initially thought to be a tumor suppression mechanism, as proposed by the studies demonstrating the monoallelic loss of the essential autophagy gene ATG6/BECN1 in 40–75% of human prostate, breast, and ovarian cancers." (PMID 34257560, 2021). "BRCA1 deficiency was shown to promote BECLIN 1-dependent autophagy that protected ovarian cancer cells (and benign ovarian epithelial cells) from toxic metabolic stress." (PMID 33670664, 2021). "The results support monoallelic loss of BECN1 as permissive for tumor initiation and potentiating for genomic instability in ovarian cancer." (PMID 31923184, 2020). "We further investigated the causal role of Becn1 haploinsufficiency for oncogenesis in a MISIIR SV40 large T antigen driven spontaneous ovarian cancer mouse model." (PMID 31923184, 2020). "The IPMK gene has been shown to be involved in cell cycle arrest and apoptosis in ovarian cancer and the BECN1 gene has been suggested to be a tumor-suppressor gene and its expression levels to be associated with ovarian cancer prognosis." (PMID 30416686, 2018). "Consistent with the results obtained in cholangiocarcinoma, bladder, and ovarian cancers, we demonstrated that decreased Beclin-1 expression was associated with unfavorable outcome in HCC patients." (PMID 30107804, 2018). "Previous studies have reported that the depletion of the autophagy-related gene BECN1 (encoded for Beclin 1) is observed in a variety of human breast, prostate, and ovarian cancers." (PMID 30400561, 2018). "The downexpression of Beclin-1 is ovarian epithelial cancer associated with prognosis in ovarian cancer, and the expression of LC3-II is associated with a good prognosis of hepatocellular carcinoma." (PMID 30013454, 2018). "Our unpublished data support the view that high infiltration of CAFs associates with a low level of Beclin‐1‐dependent autophagy in ovarian cancer cells." (PMID 28926101, 2018). "It has been reported low expression of Beclin 1 was associated with poor survival in Bcl-xL overexpressed ovarian cancer and hepatocellular carcinoma." (PMID 25762626, 2015). "Heterozygous loss of the canonical autophagy gene BECN1 is well documented in epithelial ovarian cancer cells." (PMID 26239434, 2015).
ovarian carcinoma (continued). "Our study shows that high Beclin 1 levels are associated with a lower risk of death in patients with ovarian cancer." (PMID 24675697, 2014). "Altogether, these observations support the content that the high expression of BECLIN 1 in ovarian carcinomas associates with a better prognosis." (PMID 25136588, 2014). "The heterozygous deletion of the autophagy gene BECLIN 1 in transgenic mice predisposes to the development of spontaneous tumours, including ovarian cancers." (PMID 25136588, 2014). "The results showed that surgical stage and Beclin 1 expression were independent risk factors for ovarian cancer prognosis." (PMID 24675697, 2014). "The monoallelic deletion of BECLIN 1 in mice caused the spontaneous development of tumours, including ovarian cancer, in association with reduced autophagy." (PMID 25136588, 2014). "In one study, the expression of BECLIN 1 was inversely correlated with the histologic grade of differentiation of ovarian carcinomas and the high level of BECLIN 1 expression was associated with a lower relapse-free survival rate of the patients." (PMID 25136588, 2014). "The surgical stage and Beclin 1 expression were both independent risk factors for ovarian cancer prognosis (both p < 0.05)." (PMID 24675697, 2014). "More importantly, stratified survival analysis of histological grade, pT/pN/pM status and clinical stage showed that Beclin 1 expression was also linked closely to survival of different subsets of patients with ovarian carcinoma." (PMID 23573264, 2013). "We now report that decreased expression of Beclin 1 is closely associated with a more aggressive phenotype and/or poor prognosis of ovarian carcinoma synergized with increased expression of Bcl-xL." (PMID 23573264, 2013). "45–75% of cases of human prostate, breast and ovarian cancers present monoallelic mutations of the Beclin-1 gene." (PMID 23071566, 2012). "Moreover, deletion of the gene that encodes Beclin‐1, another component of the autophagy machinery, has been identified in ovarian cancers." (PMID 37526235, 2023). "Moreover, data from patients with ovarian cancer and lymphomas indicate that higher levels of BECN1 are associated with a better prognosis and higher survival rate." (PMID 36008963, 2022). "Furthermore, Becn1 loss is frequently observed in different forms of cancer, such as breast, prostate and ovarian cancers, besides BECN1 loss in malignant epithelial ovarian cancer." (PMID 36497321, 2022). "Furthermore, autophagy-deficient ovarian cancer cells display increased ROS and a decrease in autophagy due to the knock-down of BECN1, leading to the up-regulation of ROS and NF-κB activation." (PMID 32432106, 2020). "Indeed, BECN1 (encoding Beclin-1), which is associated with the formation of the autophagosome, is often deleted in breast and ovarian cancer." (PMID 30344951, 2018). "The examination of Beclin 1 expression, by IHC, therefore, could be used as an additional effective tool in identifying those ovarian carcinoma patients at increased risk of tumor invasion and/or progression." (PMID 23573264, 2013). "Furthermore, the differences in expression were significant, which suggested that decreased Beclin-1 expression, and the activity of macrophages, may be associated with chemotherapy resistance and poor prognoses in patients with ovarian cancer." (PMID 25789037, 2015).
ovarian carcinoma (continued). "Our findings suggest that Beclin 1 expression, as examined by IHC, could be served as an additional tool in identifying ovarian carcinoma patients at risk of tumor progression, and predicting patient survival in ovarian carcinomas with increased expression of Bcl-xL." (PMID 23573264, 2013). "This discovery indicates that PTEN and Beclin-1 play roles in regulating autophagy in ovarian cancer, and their decreased expression levels contribute to reducing autophagy activity and increasing chemoresistance." (PMID 39273093, 2024). "In a mouse model, haploinsufficiency of BECN1 was observed to allow and enhance genomic instability in ovarian cancer." (PMID 38398197, 2024). "In epithelial ovarian cancer, circMUC16 can promote the expression of Beclin-1 and Runx1 by sponging miR-199a-5p, thus promoting autophagy." (PMID 38338839, 2024). "Autophagy has a protective role in regulating cellular chemo-sensitivity to cisplatin, specially in human ovarian cancer and can be inhibited by autophagy inhibitors and BECN1 small interfering RNA." (PMID 39695078, 2024). "We found that LOC730101 specifically binds to the autophagy key protein BECN1 in ovarian cancer cells." (PMID 39695078, 2024). "CircRNF144B promotes the ubiquitination of Beclin-1 by sponging injection of miR-11-342p, thereby inhibiting autophagic flux and promoting ovarian cancer progression." (PMID 38338839, 2024). "Early reports of monoallelic loss of the beclin 1 (BECN1) encoding gene in 40 to 75% of breast, prostate, and ovarian cancers led to describing autophagy as a tumor suppressor." (PMID 37808004, 2023). "In human breast and ovarian cancers, allelic deletion of the autophagy gene BECN1 has been documented." (PMID 36998052, 2023). "Beclin-1 expression has been found to be downregulated in ovarian cancers compared to benign lesions, suggesting the predictive potential of the beclin-1 protein in OC." (PMID 35203301, 2022). "Here, we expand on the previous studies by investigating the BECN1 isoforms isolated from ovarian cancer cells." (PMID 36008963, 2022). "The same results have been demonstrated in human cancers, where Beclin 1 expression was reduced in a number of human cancers, including glioblastoma, ovarian cancer, and esophageal cancer 117-119." (PMID 36147481, 2022). "CD147 can inhibit autophagy by inhibiting PI3K signal pathway and down-regulating autophagy-related gene 6 (ATG6, Beclin 1) expression in ovarian cancer cells." (PMID 36483594, 2022). "Cancer cell dormancy and autophagy are interconnected at the molecular level through ARH-I (DIRAS3) and BECLIN-1, two tumor suppressors often dysregulated in ovarian cancers." (PMID 35565270, 2022). "The monoallele deletion of BECN1 also accelerated tumorigenesis in mice in the ovarian cancer model, suggesting that autophagy is a suppressor of ovarian cancer." (PMID 36147481, 2022). "BECN1 cloning and sequencing analysis were performed also starting from the mRNA isolated from the ovarian cancer cell line A2780 for NIHOVCAR3." (PMID 36008963, 2022). "In an advanced stage of ovarian cancer, low expression of BECN1 and high level of BCL-2 (anti-apoptotic protein) was associated with poor prognosis." (PMID 33670664, 2021). "Accordingly, the expression of BECN1 was found significantly higher in benign and borderline ovarian cancer than in aggressive ovarian cancer, and inversely correlated with the increasing FIGO stage and histologic grade of malignant EOC." (PMID 33670664, 2021). "Yet, another study found that the expression of BECLIN 1 protein was stronger in ovarian carcinoma than that in normal ovary and benign tumor." (PMID 33670664, 2021). "Autophagy was initially thought to be a tumor suppression mechanism, as suggested by early studies reporting the monoallelic loss of the essential autophagy gene ATG6/BECN1 in 40–75% of human prostate, breast, and ovarian cancers." (PMID 34257560, 2021).
ovarian carcinoma (continued). "We found that decreased expression of BECN1 and BRCA1 in ovarian cancers was significantly associated with high DNA methylation of these genes." (PMID 33670664, 2021). "In the 316 ovarian cancers in TCGA, BECN1 and BRCA1 were shallow (monoallelic) deleted in 242 (76.6%) and 240 (76%) cases, respectively." (PMID 33670664, 2021). "Becn1+/- murine tumors and autophagy suppressed human ovarian cancer cell lines displayed greater rates of chromosomal aberrations." (PMID 31923184, 2020). "To investigate the effects of BECN1 haploinsufficiency in ovarian cancer, we developed a pseudo-haploinsufficiency knockdown model using a human ovarian cancer cell line that is atypically autophagy-competent." (PMID 31923184, 2020). "This study is the first to directly test the role of Becn1 haploinsufficiency in an ovarian cancer oncogenesis model." (PMID 31923184, 2020). "Extending these studies in a murine spontaneous ovarian cancer model, we found that tumors initiate earlier in Becn1+/- mice relative to Becn1+/+ littermates." (PMID 31923184, 2020). "Surprisingly, our data show that modest reduction of LC3B yields oncogenic phenotypes in ovarian cancer, similar to reduction of BECN1." (PMID 31923184, 2020). "Previously, Beclin 1 overexpression in ovarian cancer was reported to negatively correlate with the differentiation and higher cumulative and relapse-free survival rates." (PMID 33425768, 2020). "The significance of exclusive deletions of only BECN1 in human breast and ovarian cancer has been debated." (PMID 31923184, 2020). "Autophagy, particularly with BECN1, has paradoxically been highlighted as tumor promoting in Ras-driven cancers, but potentially tumor suppressing in breast and ovarian cancers." (PMID 31923184, 2020). "The essential Atg6/Beclin 1 gene was found to be lost monoallelically in 40–75 % of human prostate, breast, and ovarian cancers, whereas excessive autophagy stimulation by Beclin 1 overexpression has been reported to inhibit tumor progression." (PMID 31277291, 2019). "Discovery of single copy loss of the BECN1/Beclin1 gene, also known as the mammalian ortholog of yeast ATG6, in ovarian cancers provided more direct evidence of the tumor-suppressing properties of autophagy." (PMID 31438969, 2019). "Decreased autophagy promotes tumorigenesis because monoallelical loss of essential autophagy gene ATG6/BECN1 in 40–75% of in human prostate, breast, and ovarian cancers is observed." (PMID 31216334, 2019). "Beclin-1 has been considered a potential prognostic biomarker in several types of cancer including salivary gland adenoid cystic cancer, ovarian cancer, and lung cancer." (PMID 29545906, 2018). "CoQ0-induced elevated Beclin-1/Bcl-2 ratio and Bax/Bcl-2 ratio in ovarian cancer cells suggest that CoQ0 promotes cell death via pro-apoptotic signals." (PMID 28808311, 2017). "It was reported autophagy activated by proteasome inhibitors and arsenic trioxide is concomitant with reduction in Beclin-1 expression in ovarian carcinoma cells; suggesting a Beclin-1-independent pathway." (PMID 28158287, 2017). "For example, monoallelic deletions and lower BECN1 protein levels were found in human prostate, breast, and ovarian cancers tissues that were analyzed." (PMID 28459042, 2017). "High expression of Beclin-1 has been reported in ovarian cancer, GC, nasopharyngeal carcinoma, intrahepatic cholangiocarcinoma, while low expression has been reported in hepatocellular carcinoma and colorectal cancer." (PMID 28070138, 2016). "This work is the first to describe retained Beclin-1 protein expression in hemizygous tumors and to systematically assess Beclin-1-independent autophagy in ovarian cancer." (PMID 26239434, 2015).
ovarian carcinoma (continued). "The study aimed to investigate the role of Beclin-1 and PTEN, and the association with resistance in ovarian cancer." (PMID 25789037, 2015). "Knockdown of BECN1 and other autophagy-related gene expression was achieved using siRNA in established human ovarian cancer cell lines (CaOV3, OVCAR8, SKOV3, and HeyA8) and a novel early-passage, ascites-derived cell line (iOvCa147-E2)." (PMID 26239434, 2015). "Collectively, these data show that the level of Beclin-1 protein in epithelial ovarian cancer specimens falls within an easily detectable narrow range regardless of copy number." (PMID 26239434, 2015). "The low expression of the Beclin-1 and PTEN proteins in the ovarian cancer tissues was revealed to be closely associated with drug resistance." (PMID 25789037, 2015). "In conclusion, higher levels of autophagy were observed in cisplatin-resistant ovarian cancer cells, whereas knockdown of Beclin 1 expression restored cisplatin-sensitivity to these cells, which is attributed to autophagy inhibition." (PMID 25322694, 2015). "The protein expression of the phosphatase and tensin homolog (PTEN) and the BECN1 gene product, Beclin-1, was analyzed using immunohistochemistry in the 40 patients with ovarian carcinoma." (PMID 25789037, 2015). "Overall, this work makes novel observations about tumor expression of Beclin-1 and challenges the accepted understanding of its role in regulating autophagy in ovarian cancer." (PMID 26239434, 2015). "As the first discovered autophagy effector in mammalian, Beclin 1 is has been demonstrated to be deleted or decreased mono-allelically in human breast, prostate and ovarian cancers." (PMID 25762626, 2015). "The correlation analysis revealed that the intensity of Beclin-1 expression was positively correlated with the expression of PTEN in the 40 cases of ovarian cancer (P<0.05)." (PMID 25789037, 2015). "In ovarian cancer, prevalent mono-allelic deletion of BECN1 (a canonical autophagy-inducer) suggests that autophagy is impaired to promote carcinogenesis and that Beclin-1 is a haploinsufficient tumor suppressor." (PMID 26239434, 2015). "The aim of the present study was to investigate the protein expression of the autophagy-related genes, BECN1 and PTEN, and the association with drug resistance in epithelial ovarian cancers." (PMID 25789037, 2015). "The apparent dispensability of Beclin-1 for autophagy induction in ovarian cancer cell lines and its role in contributing to cell viability in HeyA8 and iOvCa147-E2 cells suggests that it has other functions in cancer." (PMID 26239434, 2015). "In the 40 cases of ovarian cancer included in the present study, the expression of Beclin-1 was revealed to be primarily located in the cytoplasm." (PMID 25789037, 2015). "The present study revealed that Beclin-1 protein expression was significantly lower in the drug-resistant group of ovarian cancer tissues compared with the drug-sensitive group." (PMID 25789037, 2015). "Even in ovarian cancer, Beclin-1-independent autophagy has been reported in the context of non-canonical stimuli such as arsenic trioxide and prolactin receptor antagonism." (PMID 26239434, 2015). "In conclusion, our findings challenge the accepted relationship between Beclin-1 and autophagy in ovarian cancer and prompt a re-evaluation of the existing model." (PMID 26239434, 2015). "Further study is required to investigate the possibility of targeting Beclin 1 in the treatment of ovarian cancer." (PMID 24675697, 2014). "The presence and the cytoplasmic distribution of BECLIN 1 were first analysed by immunohistochemistry (IHC) in paraffin-embedded tissue sections of ovary carcinomas." (PMID 25136588, 2014). "Here we have analysed the tissue expression of BECLIN 1 in a series of 61 cases of ovarian carcinomas of various histologic types." (PMID 25136588, 2014). "In total, 148 cases of ovarian cancer were divided into a Beclin 1 high-expression group (++/+++) and a Beclin 1 low-expression group (−/+)." (PMID 24675697, 2014).